TNS1 (tensin 1)
Diseases named in the same sentence as TNS1 in open-access papers (continued):
Sharing a sentence is not in itself a finding about the gene and the disease.
tumor (27 papers, 2015 to 2026). "In BCa tissues, lncRNA MAGI2-AS3, and TNS1 mRNA are expressed at low levels, and miR-31-5p is highly expressed, whereas in BCA patients, low expression levels of TNS1 are associated with tumor progression and poor prognosis." (PMID 36358270, 2022). "Tensin 1 (TNS1) is a focal adhesion molecule that has been implicated in the migration of normal and tumor cells." (PMID 33231563, 2020). "One study demonstrated that TNS1 was expressed in normal tissues but had greatly reduced expression in tumor tissues and was associated with tumorigenesis." (PMID 32315285, 2020). "TNS1 is implicated in tumor development; however, the role of TNS1 in tumors is controversial." (PMID 36358270, 2022). "TNS1 encodes tensin 1, which localizes to focal adhesion and acts as a tumor suppressor in PCa." (PMID 27626693, 2016). "CPLF primarily reflects extracellular matrix deposition in the tumour microenvironment, with Tensin 1 (TNS1) and Fermitin family homologue 2 (FERMT2) as the highest-weighted features." (PMID 41405822, 2025). "IHC staining revealed that COL14A1 and TNS1 were over-expressed in peritoneal metastatic lesions relative to primary tumor tissues." (PMID 35515139, 2022). "TNS1 was a direct target of miR-31-5p, the tumor-promoting effects of miR-31-5p on LUAD cell functions are attenuated by TNS1 overexpression to some extent." (PMID 36051999, 2022). "Noticeably, correlation analysis demonstrated that in NSCLC tumor tissues, miR-152 expression was negatively correlated with TNS1 expression." (PMID 33269380, 2021). "In tumor cells of all cases, we observed both membranous and cytoplasmic expressions of TNS1, TNS2, and TNS3 proteins." (PMID 33926026, 2021). "TNS1 expression was significantly correlated with tumor purity, macrophages (r = 0.602, P = 3.15e–41), CD4+ T cells (r = 0.527, P = 3.92e–30), dendritic cells (r = 0.468, P = 3.19e–23), and neutrophils (r = 0.403, P = 4.38e–17)." (PMID 32315285, 2020). "This is consistent with a recent study that found that TNS1 level was negatively correlated with miR-31 in COAD tumor tissues." (PMID 32315285, 2020). "Together with findings from the previous figures, these data suggest that TG2 mediates the presence of TNS1 in tumor-derived EVs, leading to FN fibrillogenesis and promotion of metastasis." (PMID 32054828, 2020). "In LSCC, a hypoxic tumor microenvironment exposed to xenobiotic toxicity nicotine can potentially cause the dysregulation of IGF-1R, ITGB1 and TNS1 signaling pathways." (PMID 31217907, 2019). "More importantly, prior studies have reported that increased expression of TNS1 correlates with tumor cell migration and identified TNS1 as a candidate oncogene in CRC." (PMID 29416680, 2018). "Functionally, knockdown of Tensin 1 or FERMT2 in fibroblasts attenuated tumour growth in vivo." (PMID 41405822, 2025). "TNS1 has been shown to positively regulate tumor progression." (PMID 36358270, 2022). "However, TNS1 was reported to be significantly upregulated in various tumor tissues as well as cell line-based studies." (PMID 34083590, 2021). "Therefore, our results demonstrate that low TNS1 expression correlates with tumor progression and poor prognosis in BCa patients." (PMID 33231563, 2020). "Moreover, immunohistochemical staining of paired BCa and normal urothelial tissues showed that low expression of TNS1 correlated with advanced tumor (T) stages and lymph node metastasis in BCa." (PMID 33231563, 2020). "Prior studies show that increased expression of Tensin 1 correlates with tumor cell migration." (PMID 26847345, 2016). "TNS1 may regulate the hippo signaling pathway by affecting RhoGAP and regulates cell proliferation and proliferation, which is important for the development of tumor." (PMID 36358270, 2022). "Therefore, TNS1 may regulate the hippo signaling pathway by affecting RhoGAP and regulates cell proliferation, which is important for the development of tumor." (PMID 36358270, 2022).
tumor (continued). "Hic‐5 (TGFβ1i1) could control tumor extracellular matrix remodeling through interaction with TNS1." (PMID 32027093, 2020). "However, whether miR-31 interacts with tumor-infiltrating immune cells by targeting TNS1 and whether miR-31 plays different roles in CRC according to microsatellite instability status warrant further investigation." (PMID 32315285, 2020). "We postulated that TNS1 may be related to tumor progression in BCa." (PMID 33231563, 2020). "Collectively, these results demonstrate that knockdown of fibroblast-derived TNS1 and FERMT2 impedes CRC tumour growth." (PMID 41405822, 2025). "Based on our findings, we conclude that myofibroblast-derived CRC, TNS1, and FERMT2 orchestrate tumour progression by upregulating FN1, which subsequently activates integrin and FAK signaling in cancer cells." (PMID 41405822, 2025). "QRT-PCR analysis demonstrated that TNS1 and MET were significantly up regulated in all EOCRC tumor samples." (PMID 34083590, 2021). "A microscopic analysis demonstrated that positive expression of TNS1, TNS2 and TNS3 proteins in tumor cells was present in 7 (7.78%), 4 (4.44%) and 32 (35.56%) out of 90 patients, respectively." (PMID 33926026, 2021). "Immune infiltrate correlation analysis indicates that TNS1 is strongly correlated with macrophages, which are the most abundant hematopoietic cells in the COAD tumor microenvironment (TME)." (PMID 32315285, 2020). "Unfortunately, most experimental studies have not established a link to these mechanisms but have only explored the positive or negative effects of TNS1 on tumor progression, leaving the relevant mechanisms unclear." (PMID 36358270, 2022). "According to existing research, TNS1 is closely related to tumors, but TNS1 is not a key oncogene; it only affects tumor progression, and there are no clinical drugs that directly target TNS1." (PMID 36358270, 2022). "Further studies revealed that TG2 promoted EMT and promoted metastasis by inducing EVs to produce TNS1; the deletion of TG2 or TNS1 significantly decreased EVs migration and did not affect primary tumor growth." (PMID 36358270, 2022). "An increase in the betweenness centrality of a node/gene in tumor samples indicates that the gene lies on shorter paths connecting other genes, suggesting its role as a bridge in tumor-related PPIs, for instance, VCL, FLNA, TNS1, GATA3, and ITGB3, which may act as key connectors in tumor samples." (PMID 40626556, 2025). "We noted that the positive expression of TNS1 and TNS2 was not common in tumor cells, whereas the positive expression of TNS3 occurred in tumor cells of about one-third of GC patients." (PMID 33926026, 2021).
cancer (26 papers, 2013 to 2026). A tumor composed of atypical neoplastic, often pleomorphic cells that invade other tissues. "Several studies have also reported that the loss of TNS1 can lead to a reduction in the migratory ability of numerous types of cancer cells." (PMID 36581942, 2022). "Furthermore, TNS1 has also been demonstrated to be associated with the EMT process of cancer cells." (PMID 36581942, 2022). "For example, resveratrol significantly upregulates TNS1 expression in different cancer cells and exerts anticancer effects." (PMID 36358270, 2022). "It has been reported that TNS1 exerted an oncogenic role in the progression of several types of cancers via regulating the expression of genes related to cell motility." (PMID 34368222, 2021). "Tensins are a family of focal adhesion proteins, composed of four members (Tensin 1–4, TNS1-4), which link the cell membrane to the actin cytoskeleton and are lost in most cancer cell lines." (PMID 34411095, 2021). "The fact that cancer cells secrete TNS1 suggests that it could be investigated as a potential target for liquid biopsies." (PMID 41923376, 2026). "TNS1 is reported to play different roles in different cancers." (PMID 33269380, 2021). "It is possible that loss of PP1cα may impact tensin 1-induced cytoskeletal reorganization in platelets to potentiate outside–in signaling, as there is precedence for tensin 1 to engage integrin β3 and disruption of PP1cα-tensin interaction enhanced cell migration and invasion of cancer cells." (PMID 37887268, 2023). "To investigate how TNS1 and FERMT2 expression in myofibroblast promotes cancer progression, we quantified the activities of 284 signaling pathways in CPTAC-2 proteomic data." (PMID 41405822, 2025). "Many of the top overexpressed (e.g., FSTL1, TNS1, DDR2, or VWF) or underexpressed genes were suggested to promote invasion and/or metastasis in different cancer types." (PMID 36359790, 2022). "Forty-eight hours after transfecting siRNA into the cancer cells, a drastic drop in the expression level of COL14A1 and TNS1 was assessed by qRT-PCR." (PMID 35515139, 2022). "From these data, we selected potential biomarkers of cancer including six upregulated proteins (RNF213, CTSG, PGLYRP1, RPL8, S100A8, S100A9) and two downregulated proteins (GPX1, TNS1)." (PMID 34361002, 2021). "Furthermore, the expression of top 5 genes (DCHS1, PRKG1, TGFBR2, TNS1, and TTC28) in the majority of detailed cancer types was shown in the form of heatmap." (PMID 36051999, 2022). "As a result, the GO functions for DACT3, TNS1, and MSRB3 included actin binding, actin cytoskeleton, negative regulation of immune system process, and cell adhesion molecule binding, which were well-recognized biological processes for metastasis of cancers." (PMID 34368222, 2021). "As the interaction of PURB with MaTAR25 is essential for PURB binding to Tns1 DNA this suggests that MaTAR25 acts as a chaperone and/or scaffold for the MaTAR25/PURB/Tns1 DNA complex, which is critical for transcriptional regulation of Tns1 thereby impacting cancer progression." (PMID 33353933, 2020).
kidney disease (2 papers, 2021). "Taken together with the role of tensin 1 in diseases, it is apparent that the pseudophosphatase members of the tensin family may serve as targets for therapeutic interventions in renal disease, cancers, breast, liver, etc., and COPD." (PMID 34203203, 2021).
cardiac disease (1 paper, 2022). "Combined with the genome-wide association study (GWAS) analysis, cardiac disease-associated genes Rasd1, Thsd7a, Ednra, and Tns1 were identified." (PMID 35938163, 2022).
infection (1 paper, 2021). The state of being infected such as from the introduction of a foreign agent such as serum, vaccine, antigenic substance or organism. "Cluster 4 included sites presenting decreased phosphorylation intensities due to the infection of RBCs (Y359 of Band 3, S1381 of Tensin-1, S365 and S366 of Serine/threonine-protein kinase MARK2)." (PMID 33842387, 2021).
TNS1 also shares sentences with these, for which no sentence is quoted: allergic disease (2 papers); head and neck squamous cell carcinoma (2); renal failure (2); Allergy (1); Alzheimer disease (1); Angelman syndrome (1); atopic eczema (1); Cachexia (1); cardiomyopathy (1); carotid atherosclerosis (1); clear cell renal cell carcinoma (1); COVID-19 (1); Crohn disease (1); eczema (1); glomerulosclerosis (1); hay fever (1); hepatitis C virus infection (1); kidney cancer (1); kidney stone (1); lymphoma (1); meningioma (1); metastatic cancers (1); multiple myeloma (1); nephronophthisis (1); pancreatic ductal adenocarcinoma (1); peripheral T-cell lymphoma (1); pilocytic astrocytoma (1); thyroid carcinoma (1); uterine sarcomas (1).